HES1 (hes family bHLH transcription factor 1)
Diseases named in the same sentence as HES1 in open-access papers (continued):
Sharing a sentence is not in itself a finding about the gene and the disease.
neuroendocrine tumors (4 papers, 2010 to 2025). "In neuroendocrine tumors (NETs), these same signaling pathways, as well as hairy enhancer of split 1 (Hes-1)/achaete–scute complex-like 1 (ASCL-1), have been shown to impact tumorigenesis via Notch signaling." (PMID 27148486, 2016). "In NE-10 neuroendocrine tumors where δ-catenin expression was increased, Hes1 expression was diminished and E2F1 expression was increased." (PMID 21106062, 2010). "However, in MiNEN (mixed neuroendocrine/non neuroendocrine neoplasm), the expression of NOTCH1 and Hes1 is reduced or absent in the neuroendocrine cells, but both NOTCH1 and Hes1 are present in the adenomatous component, potentially indicating a possible role of NOTCH as a tumour suppressor gene." (PMID 31443481, 2019).
pancreatic ductal adenocarcinoma (4 papers, 2016 to 2023). An infiltrating adenocarcinoma that arises from the epithelial cells of the pancreas. "Recent studies have demonstrated overexpression of PDX1 and alterations in HES1 expression not only in ductal pancreatic adenocarcinoma, but also in cholangiocarcinoma and biliary intraepithelial neoplasia." (PMID 27829047, 2016). "Notch1 expression could be detectable in pancreatic ductal adenocarcinoma cases, and Notch1/Hes1 signaling is reactivated; however, Notch1 as a feto-oncoprotein is activated during organogenesis and carcinogenesis." (PMID 35154607, 2021). "Given that IGF2BP2 could directly bind to and stabilize GLUT1 mRNA in pancreatic ductal adenocarcinoma and CRC, we inferred whether HES1 modulated GLUT1 expression via IGF2BP2 in an m6A modification-dependent manner." (PMID 37957183, 2023).
prostate tumors (4 papers, 2010 to 2019). "When assessed by RT-qPCR, Hes1 and Hey1 were found significantly decreased in approximately 70% of the prostate tumors that we examined." (PMID 27384993, 2016). "In prostate tumors, the overexpression of PTOV1 was associated with decreased expression of HEY1 and HES1, and this correlation was significant in metastatic lesions." (PMID 24684754, 2014). "We have found that PC3 and CWR22-Rv1 are two prostate tumor cell lines with relatively high expression levels of both δ-catenin and Hes1." (PMID 21106062, 2010). "It was reported that γ-secretase inhibitor DAPT reduced Hes1 level in two prostate tumor cell lines, PC3 and LNCaP, in a dose-dependent manner." (PMID 21106062, 2010). "In prostate tumours, HES-1 elevated expression was also related to Notch-1 receptor activation." (PMID 31758038, 2019).
rhabdomyosarcoma (4 papers, 2015 to 2025). A rare aggressive malignant mesenchymal neoplasm arising from skeletal muscle. "In human rhabdomyosarcoma, sustained high levels of Hes1 prevent p21-mediated quiescent fibroblasts from entering prolonged cell cycle arrest-associated senescence, and its inactivation leads to spontaneous tumor cell differentiation." (PMID 40755759, 2025). "Complementary genetic and pharmacologic approaches were used to demonstrate that inhibition of the transcriptional regulator HES1 increases differentiation and impairs in vitro growth in the pediatric cancer rhabdomyosarcoma." (PMID 36037042, 2022). "Highlighting Notch-mediated maintenance of an undifferentiated state in rhabdomyosarcoma, pathway inhibition using a γ-secretase inhibitor or direct inhibition of NOTCH3, HEY1 or HES1 increases the expression of myogenic differentiation factors and drives muscle-like differentiation." (PMID 40983796, 2025). "For instance, in preclinical studies of fusion-negative rhabdomyosarcoma (FN-RMS), the small molecule inhibitor JI130 significantly inhibited tumor cell growth and promoted apoptosis by suppressing Hes1 expression." (PMID 40755759, 2025).
Stroke (4 papers, 2011 to 2021). Sudden impairment of blood flow to a part of the brain due to occlusion or rupture of an artery to the brain. "At 4 weeks, the expression levels of Hes1 mRNA transcripts of rats in the stroke and PSD groups were similar (P > 0.05)." (PMID 30386260, 2018). "At 4 weeks, compared with the stroke group, the expression of Notch1 and Hes1 mRNA transcripts in the PSD group decreased, and again increased after treatment with FXT or YNJYP." (PMID 30386260, 2018). "Ginsenoside Rg1 could promote the proliferation, differentiation, and maturity of NSCs through ERK1/2, Hes1 PI3K-AKT pathway, and p38 and JNK2 phosphorylation were under control after the admission of it in stroke models." (PMID 33716673, 2021).
thymic lymphoma (4 papers, 2009 to 2025). "C8, C11, C7, and C18 were proximal to double‐positive T cells, representing thymic lymphoma characterised by elevated expression levels of genes like Notch1, Hes1 and Desi1,72, 73 along with markers associated with thymic T‐cell development such as Rag1/2, Xrcc6 and Dntt74." (PMID 40887856, 2025). "In the thymic lymphomas, this discordance is evident in the persistent expression of Notch1, Hes1 and p21, as well as the persistent expression of Ikaros isoforms normally seen in the DN3 stage." (PMID 37160922, 2023). "As a positive control for Deltex1 and Hes1 expression, we used the immature DN S49 thymic lymphoma cells (lane 5) that endogenously express Bcl-2 and active Notch1." (PMID 22319533, 2012). "When Hes1 transgenic mice were crossed with these mice, the resulting trans-heterozygotes expressing both Hes1 and Id1 developed thymic lymphomas at 100% frequency within 25 weeks and with a median onset of only 14 weeks." (PMID 19688092, 2009). "Hes1 transgenic mice develop thymic lymphomas at about 20 weeks of age with a low penetrance." (PMID 19688092, 2009). "We generated cDNA from RNA isolated from various thymocyte populations of 3 week-old wild type and Hes1 transgenic mice, which did not exhibit any sign of thymic lymphoma." (PMID 19688092, 2009).
acute lymphoblastic leukemia (3 papers, 2013 to 2019). Leukemia with an acute onset, characterized by the presence of lymphoblasts in the bone marrow and the peripheral blood. "Overexpression of Notch and/or HES1 is associated with a variety of human cancers including T-cell acute lymphoblastic leukemia (ALL), and ovarian, breast, cervical, prostate, colon and non-small cell lung cancers." (PMID 23816051, 2013).
Alzheimer disease (3 papers, 2017 to 2024). A progressive, neurodegenerative disease characterized by loss of function and death of nerve cells in several areas of the brain leading to loss of cognitive function such as memory and language. "Studies have linked Hes1, a member of the Hes1-7 family, to neural plasticity underlying learning and memory and to the pathogenesis of Alzheimer’s disease." (PMID 31454988, 2019). "These categories include WNT (WNT1, WNT3A, WNT6, AXIN2, TNF2, MMP7), Alzheimer disease presenilin (WNT1, WNT3A, WNT6, MMP7), cadherin (WNT1, WNT3A, WNT6) and Notch (LFNG, HES1) signaling pathways." (PMID 38928376, 2024).
asthma (3 papers, 2019 to 2022). "Some DEGs from this comparison, such as Fos, Jun, Hes1, Cd14, and C3, have been associated with asthma pathogenesis." (PMID 35627266, 2022). "In a study of asthma pathogenesis, inhibition of Notch/Hes1 promotes PTEN expression, which is an antagonist of PI3K/Akt pathway." (PMID 34220548, 2021). "Hes1 expression levels in healthy and asthma pathway inhibition groups were lower than those in control groups." (PMID 31391046, 2019). "We found that the expression level of hes1 was significantly lower in the healthy and asthma pathway inhibition groups than that in the other three groups." (PMID 31391046, 2019).
bladder tumor (3 papers, 2019 to 2023). "Together, the existing literature and our data led us to propose a model in which the expression level of HHEX might show differential effects depending on the interplay with other repressors, such as HES1, and the status and the grade of bladder tumors." (PMID 36980177, 2023). "Furthermore, IHC analysis of bladder tumor tissues demonstrated decreased staining for Notch 1, Presenilin 1, Hes1 and Nicastrin in mice treated with CPX-POM." (PMID 34059639, 2021).
breast tumors (3 papers, 2013 to 2024). "Among estrogen-regulated genes, progestin/PR-A counter-regulated a distinctive subset, including breast tumor progression genes (e.g., HES1, PRKCH, ELF5, TM4SF1), leading to invasiveness." (PMID 26356672, 2015). "It is noteworthy to mention that these breast tumors appeared in the lactating gland and regressed after gland involution; the regression was independent of N1ICD activity as determined by the Hes1 expression level." (PMID 23826634, 2013).
cardiac hypertrophy (3 papers, 2018 to 2021). "Population heterogeneity undermines efforts to uncover significant HCM-associated genes, and this has recently been addressed using a personalized multi-omics approach that identified Hes1 (hairy and enhancer of split-1) as a regulator of cardiac hypertrophy." (PMID 33725119, 2021). "Specifically, Hes1 was predicted to be involved in the progression of heart damage in cardiac hypertrophy." (PMID 31380393, 2019). "This study showed that knocking down Hes1 in ventricular myocytes resulted in a reduction of up to 90% hypertrophy, confirming the role of Hes1 in cardiac hypertrophy." (PMID 31380393, 2019). "Taken together, these findings strongly suggest a role for Hes1 as a regulator of cardiac hypertrophy in vitro." (PMID 29507758, 2018). "The previous results point toward a role for Hes1 in cardiac hypertrophy and heart failure." (PMID 29507758, 2018). "To determine the function of Hes1 in the context of cardiac hypertrophy and heart failure, we performed siRNA knockdown in neonatal rat ventricular myocytes followed by treatment with beta-adrenergic agonist ISO or alpha-adrenergic agonist phenylephrine (PE) containing media." (PMID 29507758, 2018). "Finally, our approach was validated by testing Hes1’s role in cardiac hypertrophy." (PMID 29507758, 2018).
cerebral infarction (3 papers, 2021 to 2025). An ischemic condition of the brain, producing a persistent focal neurological deficit in the area of distribution of the cerebral arteries. "Knockdown of Hes1 increased cerebral infarction, worsened nervous system prognosis, and promoted ER stress-induced apoptosis." (PMID 34408630, 2021). "Furthermore, Hes1 knockdown exacerbates cerebral infarction and neurological deficits after MCAO." (PMID 36786352, 2023).
cholangiocarcinoma (3 papers, 2016 to 2021). A carcinoma that arises from the intrahepatic biliary tree (intrahepatic cholangiocarcinoma) or from the junction, or adjacent to the junction, of the right and left hepatic ducts (hilar cholangiocarcinoma). "To further explore the mechanisms of SOX1 in CCA, we detected the expression of two key proteins that interact with SOX1 (HES1, PROX1) and the signaling pathways related to cholangiocarcinoma (AKT, JNK, P38, ERK) by Western blot." (PMID 34876142, 2021).
colorectal tumors (3 papers, 2015 to 2024). "Next, we used ID1 mRNA in situ hybridization and HES1 immunohistochemistry on serial sections from colorectal tumour tissue to assess whether loss of stringency in CRC resulted in more widespread co‐localization of these pathways." (PMID 28299802, 2017). "It should be noted that a positive and significant correlation between RIP140 and HES1 expression was also noticed at the mRNA level in primary colorectal tumors and in normal adjacent tissues after reanalysis of the Colonomics dataset using the Cancertool database." (PMID 38459621, 2024).
Coronary Artery Disease (3 papers, 2018 to 2022). "Furthermore, we proposed that Notch1/Hes1 and its downstream Pten/Akt pathway might serve as novel therapeutic targets for treating ischemic heart disease in diabetic setting." (PMID 29636838, 2018). "Intriguingly, a recent study by our group found that Notch1/Hes1 activation preserved thioredoxin activity and reduced MI/R injury in an acute hyperglycemic animal model, indicating that Notch1/Hes1 signaling might play a role in ischemic heart disease under diabetic condition." (PMID 29636838, 2018).
diabetic nephropathy (3 papers, 2016 to 2025). "Numb is downregulated in diabetic nephropathy tissues and high glucose-stimulated endothelial cells, while Notch1 and Hes1 are upregulated." (PMID 40822939, 2025). "Gremlin1 and hairy enhancer of split-1 (Hes1) are elevated in human kidney epithelial cells stimulated by TGF-β and in diabetic nephropathy." (PMID 27863390, 2016).
ductal carcinoma in situ (3 papers, 2009 to 2025). "Notch signaling is aberrantly activated and HES1 is highly accumulated in human breast ductal carcinoma in situ." (PMID 35163327, 2022).
Fanconi anemia (3 papers, 2016 to 2019). Fanconi anemia (FA) is a hereditary DNA repair disorder characterized by progressive pancytopenia with bone marrow failure, variable congenital malformations and predisposition to develop hematological or solid tumors. "Duplications of HES1, a downstream effector of the NOTCH pathway associated with Fanconi anemia and blast crisis transformation in chronic myelogenous leukemia were restricted to LR samples (25%)." (PMID 27276707, 2016). "We previously found an interaction between HES1 and Fanconi anemia (FA) proteins." (PMID 29463306, 2018).
HCMV infection (3 papers, 2017 to 2021). "Our study suggests a novel mechanism linking downregulation of Hes1 protein to neurodevelopmental disorders caused by HCMV infection." (PMID 28750047, 2017). "The effect of IE1 on protein level of Hes1 in the context of HCMV infection was further tested by comparing a recombinant IE1-deficient virus (TNdlIE1) to the parental wild-type (TNwt) and a “revertant” virus (TNrvIE1), respectively." (PMID 28750047, 2017). "For example, Human Cytomegalovirus infection disrupts Hes1 protein expression whose depletion leads to NPCs cell fate disturbance, proliferation suppression and abnormal differentiation, similar to that observed in ZIKV-infected NPCs." (PMID 31282298, 2019). "Taken together, these data demonstrate that HCMV infection of NPCs results in depletion of the Hes1 protein via a mechanism that requires de novo viral protein synthesis." (PMID 28750047, 2017). "In the present study, we demonstrated that HCMV infection downregulates Hes1 protein levels in infected human NPCs." (PMID 28750047, 2017). "In the present study, we report that HCMV infection downregulates Hes1 protein levels in infected NPCs." (PMID 28750047, 2017). "HCMV infection disrupts Hes1 rhythm and downregulates Hes1 expression." (PMID 33917368, 2021). "Moreover, as an important downstream effector in Notch signaling, the regulation of Hes1 expression in NPCs is disrupted by HCMV infection." (PMID 28750047, 2017). "However, upon HCMV infection, Hes1 was observed to relocate and concentrate at sub-nuclear areas where IE1 was present at 4hpi." (PMID 28750047, 2017). "Human NPCs are fully permissive for HCMV replication, and our previous work has demonstrated that HCMV infection dysregulates NICD1 and Jag1 in NPCs, which are two essential components upstream of Hes1 in the Notch signaling pathway." (PMID 28750047, 2017). "Downregulation of Hes1 by HCMV infection and IE1 implies a novel mechanism linking Hes1 depletion to virus-induced neuropathogenesis." (PMID 28750047, 2017). "In the present study, we report for the first time that HCMV infection downregulates Hes1 protein at the level in human NPCs through IE1 via a newly identified function, which may be a key mechanism that contributes to fetal brain maldevelopment caused by congenital HCMV infection." (PMID 28750047, 2017). "Thus, de novo synthesized viral proteins, but not the input virus components, are necessary for Hes1 downregulation during HCMV infection." (PMID 28750047, 2017). "Taken together, IE1, either produced during HCMV infection or expressed in the absence of virus, downregulates the protein level of Hes1, and IE1 knock-down restores Hes1 protein level during virus infection." (PMID 28750047, 2017).
head and neck squamous cell carcinoma (3 papers, 2015 to 2025). A squamous cell carcinoma that arises from any of the following anatomic sites: lip and oral cavity, nasal cavity, paranasal sinuses, pharynx, larynx, and salivary glands. "Inhibition of the Notch/Hes1 signaling pathway using γ-secretase inhibitors significantly reduces the expression of these checkpoints in head and neck squamous cell carcinoma." (PMID 40755759, 2025). "Moreover, HES1 has been found to be overexpressed in 32% of head and neck squamous cell carcinomas (HNSCC), but only in the absence of NOTCH1-inactivating mutation." (PMID 41009728, 2025).
Hyperglycemia (3 papers, 2013 to 2023). An increased concentration of glucose in the blood. "Furthermore, MLL2 knockdown diminished intermittent hyperglycemia-mediated increase in Jagged1, Jagged2, N1-ICD, and Hes1 protein levels in HUVEC." (PMID 35392173, 2022). "Intermittent hyperglycemia-challenged EC exhibited Notch activation as detected through an increase in Notch1-intracellular domain (N1-ICD) level and heightened expression level of Notch downstream target gene Hes1." (PMID 35392173, 2022).
intestinal tumors (3 papers, 2011 to 2024). "Immunohistochemical analysis revealed that the expression of JAG2 and HES1, a downstream target of NOTCH signaling, was increased in the intestinal tumors of ApcMin/+ mice." (PMID 28881809, 2017).
myocardial infarction (3 papers, 2018 to 2025). Gross necrosis of the myocardium, as a result of interruption of the blood supply to the area, as in coronary thrombosis. "After treatment, mouse heart function, myocardial injury markers, myocardial infarction and Notch1/Hes1 expression, endoplasmic reticulum stress markers, and apoptosis-related proteins were determined." (PMID 35588098, 2022).
myocardial ischemia (3 papers, 2016 to 2025). A disorder of cardiac function caused by insufficient blood flow to the muscle tissue of the heart. "The Notch1/Hes1 signaling pathway participates in the melatonin-mediated cardioprotective effects demonstrated in both in vivo and in vitro models of myocardial ischemia–reperfusion injury." (PMID 27630117, 2016). "Recently, Yu and colleagues demonstrated that melatonin protected against myocardial ischemia–reperfusion injury via the modulation of the Notch1/Hes1 signaling pathway." (PMID 27630117, 2016). "Genes such as HES1 and NRP1 were important for progression of cardiac ischemia, but these genes may be linked with CAD." (PMID 31881747, 2019).
nephritis (3 papers, 2010 to 2022). Inflammation of renal tissue. "In murine NTS-nephritis investigated here, Hes-1 and Hey-1 mRNAs were overexpressed at 10 days." (PMID 35215234, 2022). "The results indicated that PGC-1α overexpression provides sufficient metabolic input and can reduce Notch1/Hes1 pathway activation, thereby alleviating AKI induced kidney inflammation, apoptosis and fibrosis." (PMID 35225153, 2022). "Likewise, the expression of Hes1 was scarce and limited to a few cells within the glomeruli in healthy kidneys, but it was strongly expressed in podocytes as well as in renal progenitors of patients with LES nephritis or FSGS." (PMID 20680961, 2010).
oral cancer (3 papers, 2016 to 2023). "According to certain studies, HES1 may contribute to the onset of oral cancer cells sustainably infected with P. gingivalis exhibit resistance to Taxol and have a higher metastatic potential." (PMID 36982508, 2023). "We report the molecular docking analysis data for oral cancer drug, cetuximab with NOTCH signaling pathway targets such as NOTCH1, NICD and HES1 which regulates Epithelial Mesenchymal Transition (EMT)." (PMID 37822809, 2023). "For instance, our previous study demonstrated that Hes1 is upregulated in OSCC, and the suppression of Hes1 in oral cancer cells inhibits self-renewal capacity of OSCC, suggesting the important role of Hes1 in OSCC CSC." (PMID 27259269, 2016).